PDE4D (phosphodiesterase 4D)
Diseases named in the same sentence as PDE4D in open-access papers (continued):
Sharing a sentence is not in itself a finding about the gene and the disease.
cancer (continued). "The hedgehog signaling has been reported to promote cancer cell chemoresistance, and we and colleagues have previously demonstrated that PDE4D inhibitor Eggmanone elevates cAMP which in turn activates Protein kinase A, leading to the sonic hedgehog signaling inhibition." (PMID 34066000, 2021). "Furthermore, ectopic expression of PDE4D2, a PDE4D short isoform, enhanced cancer cell proliferation, both in vitro and in vivo." (PMID 31775395, 2019). "Our finding provides a probable explanation for the response heterogeneity of MEK inhibition in cancer treatment because the regulatory effect of MEK inhibition on PDE4D activity largely depends on the cell-type/environment and finally leads to the different change of cAMP level." (PMID 30482227, 2018). "Although PDE4D copy number and, to a lesser degree, mutational status correlates with cancer incidence the role of PDE4D isoform expression has not been studied in a clinical context." (PMID 26575822, 2015). "Interestingly, our data highlighted that PDE4D silencing may affect the gene expression of several cancer-related genes in all HCC cell lines, among which emerged IGF2." (PMID 34062786, 2021). "However, the association between the EGFR signaling pathway and PDE4D has not been reported in cancer cells." (PMID 25289091, 2014). "Phosphodiesterase 4D (PDE4D) degrades cAMP and has recently been identified as an oncogene in different human cancer types." (PMID 39202484, 2024). "The potential of these 4 molecules as a novel drug target also has been shown in a variety of studies: An accumulated knowledge on AGR2, PDE4D, NINJ2 and CDC25B have accelerated the drug discovery targeting these molecules in the other cancers." (PMID 35841085, 2022). "Deletions in many of our hotspot genes (e.g., NRXN1, PDE4D, WWOX, LSAMP, and NEGR1) are also found in numerous cancers where they likely represent the effects of perturbed replication and transcription." (PMID 25373142, 2015). "For example, genes such as VEGFA and EZR were significantly expressed in EC-1-Cancer cells, but genes such as PDE4D and AFDN were not expressed." (PMID 37124501, 2023). "Interestingly, the short isoform of PDE4D, PDE4D2, has been shown to enhance cancer cell proliferation, underscoring the dual role that different isoforms of PDE4D may play in tumorigenesis." (PMID 40564004, 2025). "At present, there are no FDA-approved cancer treatments that target PDE4B, PDE4D, or SFRP5." (PMID 39202484, 2024). "Indeed, many of the most commonly deleted CFS-like genes in cancer, including A2BP1, MACROD2, and PDE4D, are not known common fragile sites even in the most recent analyses." (PMID 23805207, 2013).
psychiatric disease (6 papers, 2018 to 2023). "In addition, ATF4 has been shown to interact with Disrupted-in-Schizophrenia 1, a risk factor for major mental illnesses and regulate dopaminergic signaling by repressing transcription of phosphodiesterase 4D, a gene involved in psychiatric disorders." (PMID 37906604, 2023). "In addition, PDE4D interacts with another risk gene for mental illness, Disrupted in Schizophrenia 1 (DISC1), which anchors PDE4s to the SER where it can regulate cAMP drive on internal calcium release." (PMID 33328902, 2020). "Pten (Chr 19 male Hypothermia QTG), Rps6kb1/p70S6K (Chr 11 Mobility and male Hypothermia QTG), and Pde4d (Chr 13 female Hypothermia QTG) were the most well connected QTGs in terms of associations with drugs of abuse and psychiatric disease." (PMID 34367237, 2021).
neurodevelopmental disorder (5 papers, 2018 to 2025). A behavioral and cognitive disorder with onset during the developmental period that involves impaired or aberrant development of intellectual, motor, or social functions. "The importance of dimeric forms of PDE4D for normal brain function is underscored by the discovery of PDE4D missense mutations in an ultrarare, neurodevelopmental disorder known as acrodysostosis type 2 with or without hormone resistance." (PMID 31488603, 2019).
neurological diseases (4 papers, 2020 to 2024). "Currently, promising treatments are being developed for neurological diseases that against PDE4B and PDE4D." (PMID 34977026, 2021).
cardiac diseases (3 papers, 2010 to 2025). "On the other hand, PDE4D has already been linked to cardiac diseases and its role in heart was intensively investigated." (PMID 21151982, 2010). "Further studies are needed to titrate the dose impacts of genetic reduction of PDE4D, such as heterozygous deletion of PDE4D, in different cardiac diseases." (PMID 39662482, 2025).
cardiovascular diseases (3 papers, 2018 to 2023). "Despite the fact that PDE4A, PDE4B and PDE4D are expressed in the human and rodent heart, with PDE4D being the predominant isoform found in the human heart, there is no approval for a PDE4 inhibitor for the treatment of cardiovascular diseases." (PMID 29461511, 2018).
infection (3 papers, 2014 to 2025). The state of being infected such as from the introduction of a foreign agent such as serum, vaccine, antigenic substance or organism. "Strikingly, no synergistic effect was observed when combining DMSO with Roflumilast treatment, indicating that the infection-enhancing effect of DMSO is primarily exerted via the inhibition of PDE4D." (PMID 30955495, 2019). "A lentiviral infection technique was used to stabilize the knockdown of PDE4D, which was subsequently examined in vitro and in vivo." (PMID 25289091, 2014). "Meanwhile, we observed that certain biomarkers (SLC7A5, PDE4D, CXCR4, PER1, PIK3R1, HBA1, HBB) were elevated during the pre-infection phase (LTBI), while others (SOCS3, GZMK, HIS1H3B) were upregulated in the post-infection phase (ATB)." (PMID 40589756, 2025).
brain disorder (2 papers, 2024 to 2025). A disease affecting the brain or part of the brain. "PDE4D longform selective, allosteric compounds are under investigation for a range of brain disorders and their selectivity arises from a single amino acid difference (PDE4D vs PDE4A, 4B, 4C) in the UCR2 region." (PMID 39673076, 2024).
neurodegenerative disease (2 papers, 2022 to 2024). A disorder of the central nervous system characterized by gradual and progressive loss of neural tissue and neurologic function. "Conversely, a depletion of cAMP levels induced by the high expression of PDE4D subtypes D1 and D3 was observed in neurodegenerative diseases (e.g., AD) and associated with cognitive deterioration and neuroinflammation." (PMID 39125619, 2024).
respiratory diseases (2 papers, 2023 to 2024). "PDE4D is a cAMP-degrading phosphodiesterase that is known to have strong anti-inflammatory effect, and targeting PDE4D has been shown to be beneficial for the treatment of respiratory diseases and neurological disorders." (PMID 37914699, 2023).
gastrointestinal disorders (1 paper, 2022). "In addition, four genes PDE4D, PKP2, NLGN1 and ALDH1B1 may be candidate genes for congenital heart defects or gastrointestinal disorders in OSH." (PMID 36302822, 2022).
PDE4D also shares sentences with these, for which no sentence is quoted: Huntington disease (5 papers); bipolar disorder (3); brachydactyly mental retardation syndrome (2); genetic disease (2); ischemia (2); Parkinson’s (2); prostate adenocarcinoma (2); psoriatic arthritis (2); psychosis (2); abdominal aortic aneurysm (1); Albright hereditary osteodystrophy (1); anaplastic astrocytoma (1); anxiety disorder (1); atrial fibrillation (1); autism (1); bacterial infections (1); benign prostatic hyperplasia (1); brachydactyly (1); brain cancer (1); cardioembolic stroke (1); Cerebral ischemia (1); cervical cancer (1); CHARGE syndrome (1); cholangiocarcinoma (1); chronic lymphocytic leukemia (1); cognitive disorder (1); demyelinating disease (1); dermatophytosis (1); developmental disabilities (1); diabetic cardiomyopathy (1).
A further 40 diseases each share a sentence with PDE4D in 1 paper.